MALAT1 (metastasis associated lung adenocarcinoma transcript 1)
Diseases named in the same sentence as MALAT1 in open-access papers (continued):
Sharing a sentence is not in itself a finding about the gene and the disease.
tumor (continued). "Additionally, the abnormal expression of lncRNAs such as H19 and MALAT1 in BTC is strongly associated with tumor progression, suggesting that targeting these lncRNAs could offer new therapeutic strategies." (PMID 39857631, 2024). "Indeed, MALAT-1 knockdown using MALAT-1 antisense oligonucleotides (ASO) in an immune-competent mouse model results in a decrease in MDSC as well as immunosuppressive tumor-associated macrophages (TAM)." (PMID 38201661, 2024). "Interestingly, across all but one tumor sample, tumors had genetic variants in MALAT1." (PMID 36865335, 2023). "We next evaluated whether MALAT1 expression was associated with the clinical behavior of the tumor." (PMID 37803049, 2023). "Today, there are very few studies focusing on theassociation between MALAT1 mutations and breast cancerprogression and the clinicopathological parameters of the tumor; so, it remainsan open question whether this gene is a driver gene in breast carcinogenesis ornot." (PMID 37538803, 2023). "In order to clarify whether the expression status of MALAT1 in tumour tissues is associated with CRC prognosis or the clinical characteristics of CRC patients, we performed this prospective cohort analysis with a relatively large sample size and a long-term follow-up period." (PMID 35558512, 2022). "The different data recently collected on the lncRNA MALAT1 (metastasis-associated lung adenocarcinoma transcript 1) are an example of how a single lncRNA can simultaneously activate several strategies that promote the same phenomenon, in this case, tumour progression." (PMID 33673376, 2021). "Also, MALAT-1 has been linked to several other human tumor entities." (PMID 30352575, 2018). "Metastasis-associated lung adenocarcinoma transcript 1 (MALAT-1), an evolutionarily highly conserved and ubiquitously expressed lncRNA, was found to be highly overexpressed in several human malignancies, and associated with clinical parameters and promoted tumor cell invasion and metastasis." (PMID 25811929, 2015). "Tumor-suppressive miRNAs, such as miR-125b and miR-509-5p, are sequestered by long non-coding RNAs (lncRNAs), like MALAT1 and HOTAIR, which act as competing endogenous RNAs (ceRNAs), enhancing oncogenic signaling." (PMID 41596492, 2026). "MALAT1 also functions as a competing endogenous RNA (ceRNA), sponging tumor-suppressive miRNAs such as miR-125b, miR-1271-5p, and others, thereby promoting oncogenic pathways." (PMID 41596492, 2026). "In CC, numerous lncRNAs (e.g., HOTAIR, MALAT1) and miRNAs (e.g., miR-21, miR-34a) have been validated as oncogenes or tumor suppressors, regulating tumor progression and microenvironment remodeling through complex ceRNA networks." (PMID 41614894, 2026). "Studies indicate that high MALAT1 expression is significantly correlated with advanced tumor stage, increased recurrence rates, and reduced OS." (PMID 41584724, 2026). "Malat1 drives Wnt autocrine signaling to increase tumor cell self-renewal while increasing the expression of Serpinb6b, a protease inhibitor that suppresses gasdermin D-mediated pyroptosis by blocking the caspase-1/cathepsin G pathway." (PMID 41484089, 2026). "Through its interaction with YB1, FGF12 enhances the expression and stability of oncogenic lncRNAs, including NEAT1 and MALAT1, thereby strengthening adaptive transcriptional programs that support tumor persistence." (PMID 41294881, 2025). "While several studies have identified roles of HOTAIR, UCA1, and MALAT1 in tumor progression, the transcriptional control of these lncRNAs by BCSC-associated factors remains only partially elucidated." (PMID 40781106, 2025). "LncRNAs like HOTAIR and MALAT1 interact with the Notch signaling pathway to promote tumor cell proliferation, metastasis, and drug resistance." (PMID 40621472, 2025). "A study reported that MALAT1 can be downregulated through autophagy inhibition, which suppresses cell proliferation and tumor growth in HCC." (PMID 40699668, 2025).
tumor (continued). "Our research uniquely demonstrates that downregulation of MAP2K1 is a critical mechanism by which MALAT1 inhibition suppresses tumor progression, including proliferation, migration, and EMT processes." (PMID 39319867, 2025). "A recent study noted that the knockdown of MALAT1 led to a reduction in tumor growth and spread in vivo." (PMID 40149989, 2025). "MALAT1 is known to function as a ceRNA, sequestering tumor‐suppressive microRNAs such as miR‐561‐3P, miR‐125b, and miR‐218, thereby promoting oncogenic gene expression." (PMID 41031251, 2025). "qRT-PCR and FISH performed on paired tumor and adjacent liver tissues confirmed significantly elevated MALAT1 expression in tumor tissues, further reinforcing the robustness and translational relevance of our findings." (PMID 40860202, 2025). "Dysregulated expression of specific lncRNAs, including MRPL23-AS1, MALAT1 and GAS5, has been associated with tumor progression, poor prognosis and therapy resistance." (PMID 39895777, 2025). "Several studies reported a role for both miR-423-5p and MALAT-1 in the regulation of crucial tumor processes including proliferation, migration and cell metabolism." (PMID 41029313, 2025). "Studies in OS demonstrate that specific ncRNAs, such as lncRNA MALAT1 and circRNA hsa_circ_0001658, contribute to epigenetic regulation of tumor growth and metastasis through modulation of key oncogenic pathways such as Wnt/β-catenin and PI3K/AKT." (PMID 40868849, 2025). "In this study, we initially investigated the MALAT1 expression across various tumors and explored its correlation with tumor prognosis through comprehensive database analysis." (PMID 40597438, 2025). "Validation of the anti-tumor effectiveness of both miR-423-5p replacement and MALAT-1 downregulation through LNA Antisense GapmeR delivery was assessed in an in vivo model of HCC." (PMID 41029313, 2025). "Studies indicate that MALAT1 is highly expressed in CRC and is closely associated with tumor staging and patient prognosis." (PMID 40891683, 2025). "lncRNA MALAT1 is crucial in shaping the tumor microenvironment, particularly in regulating tumor-associated macrophages (TAMs)." (PMID 41220952, 2025). "Previous studies have also identified MALAT1 as a promising plasma-based biomarker beyond the tumor types evaluated here." (PMID 40674376, 2025). "Elevated MALAT1 expression was notably observed in tumor tissues when compared to peritumor and normal tissues." (PMID 40597438, 2025). "In the multivariate Cox regression analysis, key variables, such as age, gender, smoking status, alcohol consumption, tumor stage (T stage), nodal stage (N stage), and lncRNA MALAT1 expression levels were included." (PMID 39319867, 2025). "SOX2, PIWI proteins, and MALAT1 have been identified as potential regulators of tumor progression, offering promise for their application as plasma-based biomarkers." (PMID 40674376, 2025). "Nevertheless, these enriched pathways offer valuable insights and will be key targets for future research to further elucidate their roles in MALAT1-mediated tumor progression." (PMID 39319867, 2025). "Given that curcumin has been shown to upregulate tumor‐suppressive microRNAs, it is conceivable that NanoCurcumin modulates MALAT1 expression via a microRNA‐mediated mechanism, effectively disrupting its oncogenic ceRNA function." (PMID 41031251, 2025). "One of the most studied lncRNAs in NSCLC is the metastasis-associated lung adenocarcinoma transcript 1 (MALAT1), which is highly expressed in the serum of NSCLC patients and promotes tumor migration by inhibiting apoptosis and shortening the cell cycle." (PMID 40176898, 2025). "Melanoma studies using MALAT1-ASO further reported xenograft tumor growth inhibition and MAPK pathway rewiring." (PMID 41191214, 2025). "Corresponding xenograft models were created for these cell lines, and near-infrared fluorescence imaging assessed tumor imaging effectiveness and the biodistribution of Cy5.5-labeled MALAT1 ASOs." (PMID 40597438, 2025).
tumor (continued). "The development and proliferation of the tumor tissue in NSCLC xenografts were hampered by reduced MALAT-1 expression." (PMID 39912974, 2025). "Most importantly, CLF modulates the expression of several non-coding RNAs, including MALAT1 and NEAT1, that are linked to tumor cell proliferation, cell migration, and drug resistance." (PMID 41303378, 2025). "Functionally, our findings demonstrate that increased MAP2K1 expression counteracts the inhibitory effects observed upon lncRNA MALAT1 knockdown, thereby promoting malignant biological behaviors and tumor growth in HSCC cells." (PMID 39319867, 2025). "For example, lncRNA MALAT1 acts as a sponge for miR-145, sequestering it and preventing its tumor-suppressive role in targeting oncogenes, thereby enhancing tumor growth and metastasis in various types of cancer." (PMID 40278506, 2025). "The expression of MALAT1 in tumor cell lines (A431, A549, PC9GR, PC9) was evaluated using quantitative real-time PCR and normalized to the endogenous control GAPDH." (PMID 40597438, 2025). "The downregulation of miR-34c via CricNOTCH1 or MALAT1 overexpression promotes drug resistance by inhibiting ferroptosis and apoptosis, consistent with its role as a tumor suppressor." (PMID 39846637, 2025). "When MALAT1 was knocked down with ASO-MALAT1 in xenograft tumors derived from HBx-expressing HepG2 cells, significantly smaller tumor sizes, weights, and volumes were detected than in the HBx+ASO-NC group." (PMID 40860202, 2025). "For instance, miR-21 promotes tumor invasion and metastasis by targeting tumor suppressor genes, while long ncRNAs like H19 and MALAT1 modulate epithelial–mesenchymal transition and cell motility." (PMID 40918645, 2025). "Suppression of MALAT1 not only attenuates tumor proliferation but also limits intrahepatic expansion and peritoneal spread, supporting its therapeutic potential as a dual-target regulator of tumor progression and early dissemination." (PMID 40860202, 2025). "Altogether, our data establish that HBx promotes hepatocarcinogenesis via MALAT1 upregulation and m6A-mediated stabilization, thereby facilitating tumor growth and metastasis." (PMID 40860202, 2025). "Through dynamic fluorescence imaging in live animals using this probe, we can assess the MALAT1 expression levels in different tumors, thereby providing valuable data for tumor treatment." (PMID 40597438, 2025). "With its high expression in various tumor tissues and clinical relevance, MALAT1 emerges as a promising target for developing a molecular imaging diagnostic method." (PMID 40597438, 2025). "Among them, metastasis-associated lung adenocarcinoma transcript 1 (MALAT1), a well-studied lncRNA, exhibits aberrant expression in multiple malignancies and is closely associated with tumor growth, metastasis, and prognosis." (PMID 40958861, 2025). "The MALAT1 level and its distribution in xenograft tumor tissues were increased in the HBx group, whereas they were decreased in the ASO-MALAT1 group (." (PMID 40860202, 2025). "The dysregulation of specific lncRNAs, including LINC01140, MALAT1, HOTAIR, and H19, is closely linked to tumor progression, poor prognosis, and resistance to treatment." (PMID 40723840, 2025). "In NB, senescent tumor cells overexpress the lncRNA MALAT1, which regulates the expression of ADAM10 metalloproteinase and the consequent release from tumor cells of the NKG2D ligand MICA/B." (PMID 40496868, 2025). "Clinically, lncRNAs, such as MALAT1, HOTAIR, and H19, are associated with increased microvessel density, tumor progression, and poor prognosis." (PMID 41020820, 2025). "Research has demonstrated that M2-polarized TAMs transfer MALAT1 to tumor cells via exosomes, activating glycolysis." (PMID 41220952, 2025).
tumor (continued). "MALAT1 promotes the nuclear translocation of β‐catenin, enhancing Wnt signaling and contributing to tumor aggressiveness in HNSCC." (PMID 40231344, 2025). "Results showed a significant increase in the expression of MALAT1 in all four tumor cell lines compared to HUVEC used as a control." (PMID 40597438, 2025). "Knockdown of lncRNA MALAT1 significantly reduced tumor volume compared to the control group, while MAP2K1 overexpression produced the opposite effect." (PMID 39319867, 2025). "MALAT1 promotes TMZ chemoresistance by acting as a molecular “sponge” for tumor-suppressive miRNAs, thereby modulating the expression of target genes that control cell cycle progression and tumor growth." (PMID 40896358, 2025). "ASOs that targeted the lncRNA MALAT1 in triple-negative breast cancer has been demonstrated to alleviate malignant characteristics by reshaping tumor microenvironment." (PMID 40236651, 2025). "Curcumin has been shown to reduce the activity of oncogenic lncRNAs including H19 and MALAT1, which stops tumor cells from growing and epithelial mesenchymal transition (EMT) in cancers like breast, liver, and colorectal cancer." (PMID 41322307, 2025). "Then, cells of each group were injected into nude mice to evaluate the effect of overexpression of MALAT-1 on tumor growth in vivo." (PMID 39196297, 2024). "In another study, under hypoxic conditions, HIF-1α was shown to induce upregulation of the tumor cell MALAT1, further promoting the growth and spread of triple-negative breast cancer (TNBC) cells by autophagy activation." (PMID 39421736, 2024). "All three studies utilized tumor tissue samples as specimens to assess the expression level of MALAT1." (PMID 39471147, 2024). "Under hypoxic condition, WTAP is required for the expression of two major hypoxic markers, HIF1α and HIF1β, underlying the relevant role of MALAT1-WTAP axis in regulating adaptation of the tumor cells to hypoxia, a fundamental step in tumor progression." (PMID 38862471, 2024). "MALAT1′s roles are diverse and complex, influencing a range of cellular processes fundamental to tumor development, growth, invasion, and metastatic spread." (PMID 38791954, 2024). "By using Malat1 ASO, they found that they were able to knock down Malat1 RNA expression, which delayed primary tumor growth, decreased proliferation, and increased apoptosis." (PMID 39372872, 2024). "All prognosis studies utilized tumor tissue samples as specimens to assess the expression level of MALAT1." (PMID 39471147, 2024). "MALAT-1 serves as a competitive endogenous RNA (ceRNA) for tumor-suppressive microRNA and consequently downregulates their gene expression." (PMID 38201661, 2024). "Several genes particularly CXCL14, COX6C, CRISP3, and MPG with high expression levels in these tumor regions were identified, while healthy cells exhibited few significant genes, with only MALAT1 observed." (PMID 39764614, 2024). "The inhibition of MALAT1 significantly reduces tumor growth, invasion, and metastasis in CRC in vitro and in vivo." (PMID 39471147, 2024). "Multiple investigations have demonstrated a connection between increased MALAT-1 levels and tumor development, invasion, and metastasis in PCa." (PMID 38511067, 2024). "In conclusion, we found NCAPD3 inhibited miR-30a-5p expression to promote cell proliferation and migration and accelerate tumor growth through MALAT1 as a sponge and MYC transcriptional repression pathways." (PMID 38561330, 2024). "YAP1 has been shown to induce MALAT-1 expression, which promotes the expression of Twist, Slug, and VEGFA by sponging miR-126-5p, indicating that MALAT-1 promotes tumor metastasis by modulating EMT in CRC." (PMID 38201661, 2024). "By suppressing apoptosis, MALAT1 potentially enhances the invasiveness and metastatic potential of tumor cells, increasing the malignancy of the tumor." (PMID 39286016, 2024).
tumor (continued). "We found that miR-561-3p was downregulated in tumor samples compared to normal over expression of MALAT1 can be the probable reason for the downregulation of miR-561-3p in BC58." (PMID 38462658, 2024). "MALAT1 also facilitates TNBC progression by modulating intercellular interactions within the tumor microenvironment." (PMID 39286016, 2024). "Limited information is available concerning the interactions between MALAT1 and important tumour suppressant and carcinogenic networks in the backdrop of BC." (PMID 39323624, 2024). "Initially, MALAT1 was identified to be an oncogene promoting tumor cell proliferation, metastasis and inhibiting apoptosis." (PMID 39681821, 2024). "It was demonstrated that MALAT-1 overexpression in BC served as a tumor enhancer by actively sponging miR-561-3p." (PMID 38511067, 2024). "The relationship between MALAT-1 and tumor immunity has been the topic of several recent investigations." (PMID 38511067, 2024). "Liposome-mediated MALAT1 silencing followed by subsequent TMZ treatment demonstrated moderate but statistically significant tumor reduction coupled with overall survival benefits in vivo in moues tumor models." (PMID 39457052, 2024). "The overexpression of MALAT-1 enhances the ability of tumor cells to migrate, invade, metastasize, and escape the cytotoxic effect of chemotherapy." (PMID 38201661, 2024). "Extensive research from clinical-epidemiological studies and cell culture experiments consistently indicate that MALAT1 plays a role as a tumor promoter in GBMs, with its inhibition resulting in reduced tumor growth in a large number of preclinical GBM models." (PMID 39553554, 2024). "The study's findings revealed a strong association between the expression of MALAT-1 and BACH1 and critical clinicopathological factors, such as tumor-node-metastasis stage, metastatic progression, histopathological stage, and survival rates of TNBC patients." (PMID 38511067, 2024). "Depending on the context and cellular environment, MALAT1 can exhibit both oncogenic and tumor-suppressive functions." (PMID 39532842, 2024). "Due to the similarity of functional and molecular pathways between placental trophoblast and tumor cells, MALAT1 has also been studied in pregnancy-related diseases, but its role in regulating placental angiogenesis is under-elucidated." (PMID 39199376, 2024). "Apart from MEG3, MALAT-1 has also been extensively studied in different cancers, highlighting its role in tumor development and progression." (PMID 39448589, 2024). "We provide a novel discovery that LUAD patients with tumor stages harboring MALAT1 (rs3200401; CC and CT+TT) heterozygotes had a significantly associated with EGFR wild-type, but not in all LADC patients." (PMID 38517388, 2024). "Through direct interactions with known tumor suppressing miRNAs (MALAT1, HOTAIRM1), miRNA sponging (NEAT1, UCA1), and competition with miRNAs for mRNA binding (UCA1), lncRNAs drive oncogenesis in ATC via these dynamic interactions." (PMID 38785786, 2024). "For instance, MALAT-1 stimulates tumor development in retinoblastoma by blocking miR-124, which causes Slug, a crucial element of the MAPK/ERK pathway, to be upregulated." (PMID 38511067, 2024). "For example, the study showed that the injection of ASOs targeting lncRNA MALAT1 mitigated tumor propagation in nude mice." (PMID 39448589, 2024). "We observed a rise in MALAT1 expression, correlating with increased levels of monocyte chemoattractant protein-1 (MCP-1) and CD68, CD163, CD206, indicative of tumor-associated macrophages in lung tumors of AA patients." (PMID 38791954, 2024). "The inhibition of MALAT1 upregulated the expression of miR-1-3p via a ceRNA mechanism, which subsequently suppressed tumor cell metastasis and tumor angiogenesis by inactivating the downstream effectors Coronin-1C (CORO1C) and tropomyosin 3 (TPM3)." (PMID 38540273, 2024). "Our results agree with the role of MALAT1 as a tumor suppressor maintaining NR4A1 expression in MCF7 cells." (PMID 38791553, 2024).